SYK (spleen associated tyrosine kinase)
Diseases named in the same sentence as SYK in open-access papers (continued):
Sharing a sentence is not in itself a finding about the gene and the disease.
allergic rhinitis (2 papers, 2022 to 2025). Inflammation of the nasal mucous membranes caused by an IgE-mediated response to external allergens. "By stably binding to AMPK1, SYK, and RAC1, these components may inhibit the activation and migration of inflammatory cells and reduce the release of inflammatory mediators, thereby alleviating the symptoms of allergic rhinitis." (PMID 40732349, 2025).
ANCA-associated vasculitis (2 papers, 2023 to 2025). "An in vivo study revealed significant improvements in haematuria and proteinuria, as well as preservation of kidney function in a murine model of ANCA-associated vasculitis treated with 14 days of fostamatinib, the most notable SYK-inhibitor." (PMID 37755547, 2023).
atopic dermatitis (2 papers, 2021). "Gusacitinib and cerdulatinib inhibit JAK and SYK, both JAK and SYK are involved in the pathogenesis of atopic dermatitis." (PMID 34824210, 2021). "For example, the ASN002 (oral JAK/SYK inhibitor) induces rapid and sustained improvements in cellular infiltrates, atopic dermatitis molecular pathways, and epidermal barrier abnormalities in patients with moderate-to-severe atopic dermatitis." (PMID 33401527, 2021). "Both JAK and SYK are involved in the pathogenesis of atopic dermatitis." (PMID 34824210, 2021).
autoimmune vasculitis (2 papers, 2020 to 2023). An autoimmune form of vasculitis. "Up-regulation of SYK expression in inflamed renal and pulmonary tissue during early autoimmune vasculitis was confirmed by immunohistochemical and transcript analysis." (PMID 32305129, 2020). "Up-regulation of SYK has been demonstrated in vitro in murine kidney tissue during early autoimmune vasculitis; therefore, SYK is therefore an attractive therapeutic target for inflammatory diseases, which may include IgAV." (PMID 37755547, 2023).
bladder cancer (2 papers, 2014 to 2021). "It was found that regulators of cell cycle and cell proliferation such as S100A4, CCND2, C13ORF15 (RGCC), and SYK and genes associated with glucose or ion transport such as SLC2A3 and TMEM16A (ANO1) were upregulated in the persistently infected bladder cancer cells." (PMID 34044804, 2021).
chronic graft versus host disease (2 papers, 2017 to 2022). Chronic graft versus host disease (GVHD) is a complication that can occur after a stem cell or bone marrow transplant in which the newly transplanted donor cells attack the transplant recipient's body. "Then, spleen tyrosine kinase (SYK) has been reported as hyperphosphorylated in B-cells of murine sclerodermatous chronic graft-versus-host disease (Scl-cGVHD)." (PMID 35903091, 2022). "Recently, novel key targets and signaling pathways have been identified in the pathogenesis of chronic GVHD, including Bruton’s tyrosine kinase (BTK), Janus kinases (JAKs), spleen tyrosine kinase (SYK), and many others." (PMID 28663793, 2017).
cognitive decline (2 papers, 2021 to 2025). "Meanwhile, we also found increased SGs, SYK and p-SYK in 5XFAD Tg mice after anesthesia and surgery for the first time, which may be related to the cognitive decline of 5XFAD mice with anesthesia and surgery." (PMID 34512311, 2021).
cognitive deficits (2 papers, 2020 to 2025). "We have previously demonstrated that nilvadipine exhibits therapeutic properties by inhibiting SYK phosphorylation, which is linked to neuroinflammation, tau phosphorylation and cognitive deficits." (PMID 33076989, 2020). "The Trem2/Dap12 complex recruits spleen tyrosine kinase (SYK) through a cytoplasmic immunoreceptor tyrosine-based activation motif (ITAM), and SYK dysfunction has been shown to be associated with cognitive deficits in AD." (PMID 40234956, 2025).
ductal carcinoma in situ (2 papers, 2014 to 2019). "In samples from patients, SYK expression is lost as the tumor progresses from ductal carcinoma in situ (DCIS) to invasive breast cancer." (PMID 31178825, 2019). "Here, allelic loss of the SYK gene was explored in breast ductal carcinoma in situ (DCIS) using fluorescence in situ hybridization and pyrosequencing, respectively, and in infiltrating ductal carcinoma (IDC) using genomic data from The Cancer Genome Atlas (TCGA)." (PMID 24523870, 2014).
HCMV infection (2 papers, 2017 to 2019). "Finally, loss of SYK expression has been associated with a memory-like phenotype of NK cells after HCMV infection." (PMID 28736554, 2017). "In addition to the downregulation of PLZF, FcεRγ, SYK, and EAT-2, ml-NK cells share with cytotoxic CD8pos T cells similar genome-wide DNA methylation patterns, thus suggesting the existence of epigenetic determination programs associated with HCMV infections." (PMID 31849972, 2019). "The lack of FcεRγ, SYK, and EAT-2 in mature CD56dim NK cells is also correlated with the expansion of NKG2Cpos NK cells upon HCMV infection." (PMID 31849972, 2019).
Hepatic steatosis (2 papers, 2022 to 2024). Steatosis is a term used to denote lipid accumulation within hepatocytes. "For example, SYK is activated gradually during the progression of alcoholic or viral liver diseases, and therapeutically blocking SYK function by different chemical inhibitors significantly diminished alcohol-induced hepatic steatosis and viral hepatitis." (PMID 36568669, 2022). "The suppression of SYK activity abrogates hepatic neutrophil infiltration and resident immune cell activation, suggesting the important potential of SYK in immune cell-driven liver inflammation, liver steatosis, as well as liver cell death." (PMID 36568669, 2022).
hyperlipidemia (2 papers, 2019 to 2024). "Hyperlipidemia, SYK, and NLRP3 inflammasome are independently critical factors in various vascular injuries, but the relationship among them lacks relevant research at present." (PMID 38992615, 2024).
infiltrating ductal breast carcinomas (2 papers, 2014 to 2020). "Furthermore, no statistically relevant lower expression levels of SYK were observed in a total of 30 infiltrating lobular and 269 infiltrating ductal breast carcinomas." (PMID 32292575, 2020).
inflammatory skin disease (2 papers, 2020 to 2023). Inflammatory skin disorders covers a broad category that includes many conditions ranging in severity, from mild itching to grave medical health complications These disorders are common in people of all ages and races. "In particular, SYK has been investigated as a therapeutic target of skin inflammatory diseases such as AD." (PMID 32998341, 2020). "In summary, inhibition of SYK may be a therapeutic strategy for inflammatory skin diseases." (PMID 37506139, 2023).
lung adenocarcinoma (2 papers, 2014 to 2023). A carcinoma that arises from the lung and is characterized by the presence of malignant glandular epithelial cells. "We identified alterations in genes involved in chromatin remodeling (PBRM1, SETD2), oxidative stress (CUL3, SOD2), immune response (CSMD3, SYK), and gamma-aminobutyric acid receptor signaling (GABRD, GABRG1) in lung adenocarcinoma." (PMID 24576404, 2014).
lymph node metastasis (2 papers, 2017 to 2023). "Collectively, high SYK expression in tumor tissues was associated with lymph node metastasis, recurrence and worse overall survival." (PMID 29137391, 2017). "SYK expression among different patients’ clinicopathological characteristics indicated that high SYK expression was correlated with lymph node metastasis." (PMID 29137391, 2017). "Similarly, SYK, a cytosolic non-receptor protein tyrosine kinase, was downregulated and significantly associated with malignancy features such as tumor depth, lymphatic invasion, venous invasion, and lymph node metastasis." (PMID 36979962, 2023).
lymphoid tumors (2 papers, 2018 to 2022). "Constitutive activation of LYN and SYK has been shown to promote BTK-independent activation of the BCR cascade in ibrutinib-resistant lymphoid tumors." (PMID 35296646, 2022). "Additional therapeutic targets in lymphoid tumors addicted to chronic BCR activation include SYK, LYN, and PKCβ." (PMID 29587428, 2018). "The toxicity caused by knockdown of the essential BCR subunits CD79A/B or of downstream signaling effectors, such as BTK, SYK, and PLCγ2, observed in most ABC DLBCL cells further corroborates the notion that these lymphoid tumors critically rely on chronic active BCR signaling." (PMID 29587428, 2018).
malaria (2 papers, 2024 to 2025). Malaria is a serious and sometimes fatal disease caused by a parasite that commonly infects a certain type of mosquito which feeds on humans. "Compared with those in the malaria group, the expression levels of proteins SYK, PI3K, PLCγ2, and RAC in the spleens of mice in the ZF-CQ group increased significantly (P< 0.01 or< 0.05), and the expression levels of proteins p-MARCKS and CDC42 showed an upward trend." (PMID 41425569, 2025). "Compared with those in the control group, the expression levels of key node proteins of Fcγ R-mediated phagocytosis, including SYK, PI3K, PLCγ2, p-MARCKS, CDC42, and RAC, in the spleen samples of the malaria group decreased significantly (P< 0.01 or< 0.05)." (PMID 41425569, 2025).
mastitis (2 papers, 2019 to 2022). Inflammation of breast tissue during lactation or postpartum due to an obstructed duct or infection. "Taken together, these results provided strong evidence for the study of SNPs in bovine mastitis, and revealed the role of SYK, PTK2B, and TNFRSF21 in bovine mastitis susceptibility/tolerance." (PMID 31447828, 2019). "In this study, GO functional annotation and enrichment analysis results revealed that SYK was an important candidate gene for mastitis traits in Chinese Holstein." (PMID 36672605, 2022). "Immunofluorescence colocalization data showed that TLR4 and SYK had a high correlation in bovine mastitis mammary gland tissue and bMCEs." (PMID 36672605, 2022). "The data also showed that SYK gene expression and protein levels have a strong consistency in bovine mastitis, and NLRP3, TLR4 and IL-1β as well." (PMID 36672605, 2022). "Our previous studies successfully marked SYK as an important candidate gene for mastitis traits via GWAS and preliminarily confirmed that SYK expression is down-regulated in bMECs with LPS (E. coli) stimulation, but its work mechanism is still unclear." (PMID 36672605, 2022). "In bPBLs and bMECs, PTK2B, SYK, and TNFRSF21 are involved in different mechanisms of immune responses associated with mastitis." (PMID 31447828, 2019). "The expression levels of SYK in bPBLs and LPS-stimulated bMECs of mastitis cows were significantly down-regulated, indicating that SYK is involved in inflammatory and immune response of clinical mastitis." (PMID 31447828, 2019). "We used two-stage correlation analysis to find 27 significant SNPs associated with risk of mastitis, among which three SNPs (rs75762330, rs88640083, and rs20438858) were annotated to immune-regulated genes (PTK2B, SYK, and TNFRSF21)." (PMID 31447828, 2019). "Our previous GWAS study showed that SYK is an important candidate gene for bovine mastitis." (PMID 36672605, 2022). "Moreover, SYK protein level was also significantly down-regulated in bovine mastitis tissue, and protein levels of NLRP3, TLR4 and IL-1β were significantly up-regulated." (PMID 36672605, 2022). "SYK is an important candidate gene for mastitis resistance traits in Chinese Holstein." (PMID 36672605, 2022). "Furthermore, the PCC value of immunofluorescence colocalization of TLR4 and SYK in bovine mastitis tissue was 0.8857 (0.6 < PCC < 1.0), which was highly correlated." (PMID 36672605, 2022). "The LD block data also showed that there were strong LD relationship between rs75762330 and PTK2B, rs88640083 and SYK, rs20438858 and TNFRSF21, suggesting that these three immune-regulated genes are important candidate genes associated with mastitis traits in Chinese Holstein cows." (PMID 31447828, 2019). "Transcriptional analysis showed that PTK2B and SYK expression level was down-regulated in both bPBLs of clinical mastitis cows and in vitro LPS (E. coli)–stimulated bMECs indicating that PTK2B and SYK are important candidate genes associated with mastitis resistance traits." (PMID 31447828, 2019). "Importantly, PTK2B and SYK expression was down-regulated in both peripheral blood leukocytes (PBLs) of clinical mastitis cows and in vitro LPS (E. coli)–stimulated bovine mammary epithelial cells, while TNFRSF21 was up-regulated." (PMID 31447828, 2019). "Furthermore, SYK was down-regulated in peripheral blood neutrophils of dairy cows with mastitis (E. coli), participates in the TLR4 cascade, regulates the production of reactive oxygen species (ROS) in bovine neutrophils and affects neutrophils to kill pathogens." (PMID 36672605, 2022). "Discovery of TLR4/SYK axis may provide a new target for drug research on mastitis." (PMID 36672605, 2022). "SYK and PTK2B may be involved in the SYK/PTK2B/AKT1/JAK2 pathway in bMECs that stimulates IL-8 secretion and recruits neutrophils to kill pathogenic microorganisms, resulting in the resistance to mastitis inflammation." (PMID 31447828, 2019).
mastitis (continued). "Therefore, up-regulation of IL-10 expression in bPBLs, suggesting that IL-10 may be regulated by PTK2B and SYK, and thus participate in the regulation of inflammatory response in dairy cow mastitis." (PMID 31447828, 2019). "It showed that expression of SYK and PTK2B was down-regulated significantly (P < 0.001) in mastitis cows in comparison to the control group, while TNFRSF21 was up-regulated." (PMID 31447828, 2019). "The temporal sequences of SYK, PTK2B, TLR4, and IL-1β expression are similar, suggesting that there might be an immune response pathway in bMECs participating in bovine mastitis inflammatory response." (PMID 31447828, 2019). "Therefore, we hypothesized that SYK and TNFRSF21 may be involved in the NF-κB pathway, stimulating IL-1β secretion and promote mastitis inflammation in both bPBLs and bMECs." (PMID 31447828, 2019).
multiple myeloma (2 papers, 2021 to 2022). "Studies have shown that increased H3K36me2 in NSD2-overexpressed multiple myeloma cells is important for the transcription activation of several key oncogenes, including SYK and MYK." (PMID 34671018, 2021).
neuroblastoma (2 papers, 2019 to 2023). Neuroblastoma (NB) is the most common solid, extracranial childhood tumor. "Depletion of SYK by siRNA and the use of small molecule SYK inhibitors significantly reduced the cell viability of neuroblastoma cell lines expressing SYK protein." (PMID 30744170, 2019). "Collectively, our findings suggest that targeting SYK in combination with conventional chemotherapy should be further evaluated as a treatment option in neuroblastoma." (PMID 30744170, 2019). "We did, however, not observe any inhibitory effect on the cell viability of transfected neuroblastoma cell lines expressing exogenous SYK." (PMID 30744170, 2019). "We compared the cell viability of neuroblastoma cells treated with cytostatic drugs alone or in combination with the pharmacological SYK inhibitor BAY 61-3606." (PMID 30744170, 2019). "Inhibition of SYK using small molecule inhibitors alone or in combination with chemotherapeutic drugs as well as knockdown of SYK by siRNA impaired the cell viability of SYK expressing neuroblastoma cells." (PMID 30744170, 2019). "We observed a weaker nuclear staining of both total SYK and p-SYK in neuroblastoma cell lines as compared to neuroblastoma tissue." (PMID 30744170, 2019). "In contrast to neuroblastoma tumor tissue, SYK protein was only detected in two out of ten neuroblastoma cell lines by western blot." (PMID 30744170, 2019). "Using RT-PCR, western blot and immunocytochemistry (ICC) we examined the presence of SYK mRNA and protein in neuroblastoma cell lines." (PMID 30744170, 2019). "We observed the presence of SYK protein in the majority of neuroblastoma tissues analyzed in this study." (PMID 30744170, 2019). "While SYK protein was detected in the majority of examined neuroblastoma tissues it was less frequently observed in neuroblastoma cell lines." (PMID 30744170, 2019). "The aim of the present study was to investigate the expression of SYK in neuroblastoma tumor tissues as well as neuroblastoma cell lines and to evaluate its use as a potential therapeutic target." (PMID 30744170, 2019). "Constitutive active SYK Y130E increased cell viability of all three neuroblastoma cell lines in comparison to transfection with the empty vector independent of the presence/absence of endogenous SYK." (PMID 30744170, 2019). "In the present study, we observed that SYK expression was higher in four different neuroblastoma cohorts compared to neural crest cells and benign neurofibroma." (PMID 30744170, 2019). "In this study, we observed elevated SYK gene expression in neuroblastoma compared to neural crest and benign neurofibroma." (PMID 30744170, 2019). "In our study, we observed that siRNA-mediated SYK downregulation reduced neuroblastoma cell growth." (PMID 30744170, 2019). "The majority of the neuroblastoma cell lines express SYK mRNA at varying levels." (PMID 30744170, 2019). "This suggests that SYK has tumor-promoting functions in neuroblastoma." (PMID 30744170, 2019). "Taken together, our findings indicate a tumorigenic involvement of SYK in neuroblastoma." (PMID 30744170, 2019). "Since SYK is widely expressed by hematopoietic cells, potential negative effects on the immune cells of the tumor microenvironment have to be carefully evaluated using immunocompetent neuroblastoma animal models." (PMID 30744170, 2019). "Furthermore, we evaluated the presence of SYK protein in neuroblastoma and ganglioneuroma using immunohistochemistry (IHC)." (PMID 30744170, 2019). "To determine whether SYK inhibition could increase the efficacy of chemotherapeutic agents to inhibit neuroblastoma cell growth, we combined BAY 61-3606 with the drugs paclitaxel, cisplatin, doxorubicin, and temozolomide, respectively." (PMID 30744170, 2019). "Transient expression of a constitutive active SYK variant increased the viability of neuroblastoma cells independent of endogenous SYK levels." (PMID 30744170, 2019).